APC (APC regulator of Wnt signaling pathway)
Diseases named in the same sentence as APC in open-access papers (continued):
Sharing a sentence is not in itself a finding about the gene and the disease.
cystic fibrosis (1 paper, 2013). Autosomal recessive disorder caused by pathogenic variants in the CFTR gene (cystic fibrosis transmembrane conductance regulator), which encodes a chloride and bicarbonate channel expressed in epithelial cells, and follow the diagnosis criteria. "In particular, for molecular genetic testing, it offers specific EQA schemes for 4 diseases: Cystic Fibrosis (CFTR gene), Beta Thalassemia (HBB gene) (BT), Fragile X-Syndrome (FMR1 gene) (FX), and Familial Adenomatous Polyposis Coli (APC gene) (APC)." (PMID 23484150, 2013).
diabetic nephropathy (1 paper, 2022). "Hyperoside can improve diabetic nephropathy by targeting the miR-499-5p/APC axis and inhibiting the extracellular regulated kinase (ERK)/cAMP-response element binding protein (CREB)/miRNA-34a signalling pathway." (PMID 35566359, 2022). "Down-regulates APC expression; up-regulates miR-499e5p expression; and improves diabetic nephropathy by targeting the miR-499e5p/APC axis." (PMID 35566359, 2022).
duodenal tumors (1 paper, 2018). "In MSS tumors, the APC mutation frequency varied between segments; it was the lowest in jejunal tumors (13.6%), followed by ileal (31.3%) and duodenal tumors (37.5%)." (PMID 29522538, 2018).
dysfibrinogenemia (1 paper, 2014). "Prior to CVC implantation, patients were screened for APC resistance, protein S and protein C deficiency, and dysfibrinogenemia." (PMID 25317335, 2014).
endotoxemia (1 paper, 2017). "Here, by using the discriminating marker CD64 and a murine model of endotoxemia, we noted a rapid increase in the Mo-APC count and a decrease of cDCs numbers in spleens." (PMID 29209091, 2017).
ependymoma (1 paper, 2022). A WHO grade II, slow growing tumor of children and young adults, usually located intraventricularly. "However, pathogenic variants in the genes related to these familial syndromes (NF2, MEN1, APC, respectively) have only been observed in a few cases of sporadic ependymomas." (PMID 35689525, 2022).
familial disease (1 paper, 2023). "Although FAP is a familial disease, 11–25% of FAP patients are reported to have de novo mutations in the adenomatous polyposis coli (APC) gene." (PMID 36864485, 2023).
female sterility (1 paper, 2019). "Armadillo levels were increased in Mkrn1exS compared to controls suggesting that APC is not responsible for the Mkrn1exS female sterility phenotype." (PMID 31009498, 2019).
gastric leiomyoma (1 paper, 2014). A rare benign smooth muscle neoplasm arising from the wall of the stomach. "The methylation of MLH1, MGMT, and APC has been described in GISTs, but to the best of our knowledge this is the first time that the methylation of these genes has been associated with gastric leiomyoma." (PMID 25544907, 2014). "The genes found methylated in the gastric leiomyoma play different functions in the cell: MLH1, MSH3, MGMT, and MSH6 participate in DNA repair functions whereas APC gene participates in cell proliferation." (PMID 25544907, 2014).
Gastric Metaplasia (1 paper, 2019). Intestinal metaplasia of the gastric mucosa is an intermediate precancerous gastric lesion in the gastric cancer cascade from chronic gastritis and atrophy to dysplasia and adenocarcinoma. "For example, hypermethylation of APC, THBD, and HAND1 was associated with gastric metaplasia." (PMID 31537016, 2019).
glaucoma (1 paper, 2024). Increased pressure in the eyeball due to obstruction of the outflow of aqueous humor. "Utilizing an optimized multiplexed magnetic bead-based flow cytometry assay, we observed a dominant CD63 APC fluorescence profile in two glaucoma (GLC) samples." (PMID 39519212, 2024).
glomerular diseases (1 paper, 2016). "We checked the most important 4 genes YWHAZ, ACTB, APC, and FYN in differentially regulated genes list and found that they were all regulated in at least 3 glomerular diseases, especially the APC was regulated in all 5 glomerular diseases." (PMID 27227331, 2016).
hamartomatous polyps (1 paper, 2024). "The index case and his brother inherited the variant from their mother, who also carried a PV in the APC gene (c.3336_3340del, p.Asn1113Serfs*4) and developed CRC and histologically mixed CPs (adenomatous and hamartomatous polyps)." (PMID 39518056, 2024).
HCMV infection (1 paper, 2015). "Similarly, the involvement of APC and casein kinase 1 (CKI) in HCMV-mediated Wnt modulation remains to be explored, and might still play a significant role in regulating Axin1 stability and degradation during HCMV infection." (PMID 26729153, 2015).
hepatitis C infection (1 paper, 2016). "Although increased Beta-catenin can be seen in HCC due to APC inactivation, there are other documented causes as well, including hepatitis C infection, increased cell turnover, and mutation in other proteins involved in the molecular pathway." (PMID 27110418, 2016).
hepatocellular adenoma (1 paper, 2015). A benign epithelial neoplasm arising from the hepatocytes. "Germ-line mutations lead to truncated APC proteins, and in conjunction with a second hit, FAP-related hepatocellular adenomas have been associated with bi-allelic inactivation of the APC gene." (PMID 26404250, 2015).
hyperparathyroidism (1 paper, 2024). Hyperfunction of the parathyroid glands resulting in the overproduction of parathyroid hormone. "Molecular studies have demonstrated alterations in the adenomatous polyposis coli (APC)/β-catenin signaling pathway in these masses as well as in familial isolated hyperparathyroidism." (PMID 39611185, 2024).
Hypodontia (1 paper, 2014). The absence of five or less teeth from the normal series by a failure to develop. "Mutations in two proteins of the destruction complex, AXIN-2 and APC, while both disabling β-catenin phosphorylation and promoting its nuclear localization, have completely opposite effects in humans: mutations in AXIN-2 lead to hypodontia, mutations in APC to hyperdontia." (PMID 25339911, 2014).
idiopathic membranous nephropathy (1 paper, 2024). "Moreover, in a recent study on idiopathic membranous nephropathy (IMN), APC expression was found to be significantly decreased in IMN patients." (PMID 39328595, 2024).
influenza (1 paper, 2018). An acute viral infection of the respiratory tract, occurring in isolated cases, in epidemics, or in pandemics; it is caused by serologically different strains of viruses (influenzaviruses) designated A, B, and C, has a 3-day incubation period, and usually lasts for 3 to 10 days. "Although their APC activation capacities may differ, all tested adjuvants efficiently triggered the induction of TFH cells, which is in contrast to what we observed with aluminum salt-based or MF59®-adjuvanted influenza vaccines in neonates." (PMID 29541075, 2018).
intellectual disability syndrome (1 paper, 2024). "Homozygous ANAPC7 mutations in humans, leading to loss of APC7 protein, underlies an inherited intellectual disability syndrome, caused by defective APC/CΔAPC7-mediated degradation of the chromosome-associated protein Ki-67." (PMID 39401078, 2024).
leiomyosarcoma (1 paper, 2022). An uncommon, aggressive malignant smooth muscle neoplasm, usually occurring in post-menopausal women.
leukoplakia (1 paper, 2025). A white patch or plaque on a mucous membrane that cannot be characterized clinically or pathologically as any other disease. "By using the GEO database (GSE85195), we observed that APC mRNA levels are upregulated in leukoplakia and downregulated in late stage OSCC." (PMID 40421179, 2025). "Using a GEO database of oral carcinogenesis (GSE85195), the transcriptional modification of 19 Wnt ligands and 4 key regulatory proteins of β-catenin, including E-cadherin, APC, AXIN and GSK3B, during leukoplakia, and early and late stages OSCC, was determined." (PMID 40421179, 2025).
lipemia (1 paper, 2016). "In addition, elevation of n−3/n−6 ratio repressed mTORC1 activity and inhibited adipogenic differentiation in preadipocytes with APC knockdown, as well as alleviated hyperlipidemia in APCMin/+ mice." (PMID 27769066, 2016). "Collectively, these results suggest that the cellular productions of n-3 PUFAs and lowered n−6/n−3 ratio effectively alleviates hyperlipidemia, which is closely correlated with CRC associated with APC mutation, possibly via suppression of mTORC1 activity in adipogenesis." (PMID 27769066, 2016).
lipoma (1 paper, 2023). A benign, usually painless, well-circumscribed lipomatous tumor composed of adipose tissue. "The present study confirms as recurrent features the presence of dental anomalies and highlights the genotype–phenotype correlation between APC gene variants and skin lesions, including lipomas (as described in our patient)." (PMID 37510409, 2023).
lung acinar adenocarcinoma (1 paper, 2006). "Although it is not known whether such alterations in the APC gene affect the accumulation of the β-catenin protein in the cytoplasm and/or nucleus, accumulation of β-catenin was observed in none of the primary lung acinar adenocarcinoma samples in the present study." (PMID 16451736, 2006).
lung carcinoids (1 paper, 2020). "Mutations in other well-known negative regulators of the Wnt/β-catenin signaling cascade, such as the APC gene, were present in 6%–12% of typical/atypical lung carcinoids and in 8–23% of SI-NETs." (PMID 32033025, 2020). "Mutations in other well-known negative regulators of the Wnt/β-catenin signaling cascade, such as the APC gene, were present in 6–12% of typical/atypical lung carcinoids and in 8%–23.0% of SI-NETs." (PMID 32033025, 2020).
McCune-Albright syndrome (1 paper, 2018). McCune-Albright syndrome (MAS) is classically defined by the clinical triad of fibrous dysplasia of bone (FD), cafe-au-lait skin spots, and precocious puberty (PP). "In addition to postzygotic somatic mosaicism of GNAS in McCune-Albright syndrome, rare examples of hereditary PBMAH have been described in the setting of APC-, MEN1-, FH-, PDE8B-, and PDE11A variant-driven pathogenesis." (PMID 29594118, 2018).
metaplastic carcinomas of the breast (1 paper, 2009). "Notably, genetic alterations in different members of the Wnt signaling pathway including CTNNB1 (β-catenin), APC, and WISP3 (Wnt1 Induced Secreted Protein 3) are relatively common among metaplastic carcinomas of the breast." (PMID 19578404, 2009).
minimal change nephrotic syndrome (1 paper, 2021). "It is possible that APC C terminal mutant mice could decrease albuminuria associated with a decrease in podocyte vesicle transport with a reduction in cytoplasmic dynein-1 and α-tubulin when minimal change nephrotic syndrome is induced." (PMID 34948207, 2021).
mouth neoplasm (1 paper, 2022). "Nonetheless, the methylation of other genes in mouth neoplasm such as APC, DAPK, ECAD, RASSF1, TIMP3 and p16, have retrieved more promising diagnostic and prognostic values." (PMID 35888599, 2022).
mucinous colorectal adenocarcinoma (1 paper, 2021).
mucosal melanoma (1 paper, 2021). A melanoma that arises from a mucosal site. "When the mucosal melanoma is triple (BRAF, NRAS, NF1)-negative, KIT is the most commonly mutated gene in vulvovaginal melanomas, while APC and KRAS are detected mainly in sinonasal and anorectal melanomas, respectively." (PMID 34571863, 2021).
Multiple Endocrine Neoplasia syndromes (1 paper, 2019). "Beyond Multiple Endocrine Neoplasia syndromes, however, we report the first cases of patients with a PALB2, an APC and a NTHL1 pathogenic variants and both malignancies." (PMID 31592449, 2019).
Myalgia (1 paper, 2025). "Second, APC, ENO3, ACAD9, RNASEH1, FKTN, DYSF, and ATP2A1 are associated with Myalgia." (PMID 40831500, 2025).
myelodysplastic syndrome (1 paper, 2023). A clonal hematopoietic disorder characterized by dysplasia and ineffective hematopoiesis in one or more of the hematopoietic cell lines. "We had been interested in studying how the conditional loss of APC in LysM-Cre (LysM-Cre; ApccKO, hereafter called ApccKO) mice, which maps to the 5q deletion region, might be involved in Myelodysplastic Syndrome." (PMID 36548952, 2023).
nephrotic syndrome (1 paper, 2021). A collection of symptoms that include severe edema, proteinuria, and hypoalbuminemia; it is indicative of renal dysfunction. "Further studies will be required to clarify the specific role of APC in podocyte vesicle transport in nephrotic syndrome." (PMID 34948207, 2021). "Moreover, the greater reduction in α-tubulin and cytoplasmic dynein-1 in podocytes of APC mutant mice with nephrotic syndrome than in WT mice with nephrotic syndrome may result in a decrease in vesicle transport and albuminuria in APC C-terminal mutant mice." (PMID 34948207, 2021).
oligoastrocytoma (1 paper, 2024). A WHO grade II tumor composed of a conspicuous mixture of two distinct neoplastic cell types morphologically resembling the tumor cells in oligodendroglioma and diffuse astrocytoma.
oral cavity cancer (1 paper, 2011). A primary or metastatic malignant neoplasm involving the oral cavity. "Comparison of gene expression levels (2-ΔΔCT) of ATM and APC between patients with oral cavity cancer and healthy controls." (PMID 22414247, 2011). "Comparison of promoter methylation of APC and ATAM genes in patients with oral cavity cancer and healthy controls." (PMID 22414247, 2011).
pancreatitis (1 paper, 2022). Inflammation of the pancreas. "Idiopathic recurrent pancreatitis in FAP has been reported and may be a manifestation of the APC gene mutation." (PMID 35310730, 2022).
paraganglioma (1 paper, 2022). A benign or malignant neoplasm arising from paraganglia located along the sympathetic or parasympathetic nerves. "Similarly, we recognized that the low APC expressed in pheochromocytoma and paraganglioma can enhance the immune infiltration capacity of cancer-associated fibroblasts." (PMID 35303016, 2022).
parathyroid disease (1 paper, 2025). "Among these, several genes such as APC, CEP152, CREBBP, FAM111A, FGFR1, KL and MMP14 have been previously suggested to be associated with parathyroid disease." (PMID 40434298, 2025).
Pca (1 paper, 2022). "Mutations in SPOP, CHD1, PTEN, NKX3-1, FOXA1, and APC are other known genomic alterations in primary and advanced PCa." (PMID 36551580, 2022). "GSTP1, APC, RARB, and PITX2 are among the most extensively studied prognostic 5-mC biomarkers in Pca, and numerous reports emphasize their value as prognostic markers when analyzed in resected prostate tissues." (PMID 36551580, 2022). "Aberrant promoter hypermethylation and concomitant gene silencing have been observed at several genes in PCa, such as GSTP1, RASSF1, APC, CCND2, and PITX2." (PMID 36551580, 2022). "Various reports demonstrated that hypermethylation events at genes with prognostic implications in PCa tissue (e.g., GSTP1, APC, and PTGS2) are also detectable in plasma, serum, or urine samples." (PMID 36551580, 2022). "For instance, a urinary 4-gene 5-mC panel (i.e., GSTP1, APC, CRIP3, and HOXD8) was found to predict disease progression in patients with Gleason 6 PCa under active surveillance." (PMID 36551580, 2022). "The combined analysis of GSTP1, RASSF1, and APC showed superiority relative to the histological assessment of biopsy specimens, detecting PCa in 62 and 68% of histologically negative biopsies in two independent, large-scale studies (498 and 350 biopsies analyzed, respectively)." (PMID 36551580, 2022).
periampullary adenocarcinoma (1 paper, 2019). An adenocarcinoma that arises from the periampullary region. "Herein, we describe that the pattern of the mutational status, such as CDKN2A and APC mutations, of periampullary adenocarcinomas differs by morphologic subtype." (PMID 32914025, 2019).
periampullary adenoma (1 paper, 2025). A adenoma that involves the periampullary region of duodenum. "However, given the rarity of the presence of multiple duodenal adenomas, our findings underscore the importance of considering molecular testing for APC mosaicism, especially in the case of multiple duodenal or periampullary adenomas." (PMID 40956995, 2025).
preeclampsia (1 paper, 2024). Preeclampsia is a hypertensive disorder of pregnancy that is characterized by new-onset hypertension with proteinuria presenting after 20 weeks of gestation, and depending on mild or severe forms may initially present with severe headache, visual disturbances, and hyperreflexia. "Previous studies suggest that the number of antigen-presenting cells in the placenta of preeclampsia women is increased, but our study suggests increased activity of APc-co-inhibition pathway, this doubt still needs further study to prove." (PMID 39148025, 2024).
primary hyperparathyroidism (1 paper, 2023). "One case was a 65-year-old lady confirmed as having parathyroid carcinoma–related primary hyperparathyroidism; the other case introduced a subject with LS underlying an MLH1 gene mutation and a missense mutation of the APC (adenomatous polyposis coli) gene." (PMID 37296718, 2023).
protein c deficiency (1 paper, 2024). Protein C deficiency is a disorder that increases a person's risk to develop abnormal blood clots due to a deficiency of the Protein C, a protein in the body that prevents blood clotting. "In a predefined subgroup analyzing patients with severe protein C deficiency from the PROWESS-SHOCK, APC treatment did not result in differences in 28-day mortality (28.7% vs 30.8%, n = 673)." (PMID 38807151, 2024).
pulmonary fibrosis (1 paper, 2023). Chronic progressive interstitial lung disorder characterized by the replacement of the lung tissue by connective tissue, leading to progressive dyspnea, respiratory failure, or right heart failure. "Overall, our study provides the first evidence of the reciprocal regulation of SIRT1 stability by APC/C-Cdh1 and AROS during stress-induced premature senescence, and our findings suggest pinosylvin as a potential senolytic agent for pulmonary fibrosis." (PMID 37258580, 2023).
rectum (1 paper, 2024).
Retinal hemorrhage (1 paper, 2021). Bleeding located within the retina. "Since retinal hemorrhages can cause severe vision impairment, particularly when associated with CNV, we tested whether the APC variant 3K3A-APC, with reduced anticoagulant activity, would retain APCs’ activity and reduce CNV growth and penetration toward the sensory retina." (PMID 33652861, 2021).
round cell liposarcoma (1 paper, 2024). A poorly differentiated liposarcoma, characterized by the presence of solid sheets of primitive round mesenchymal cells and the absence of myxoid stroma. "Epigenetic analyses showed that 45% of myxoid/round-cell liposarcomas were CpG-methylated at the APC locus and had reduced APC expression." (PMID 38254762, 2024).